MTOR (mechanistic target of rapamycin kinase)
Diseases named in the same sentence as MTOR in open-access papers (continued):
Sharing a sentence is not in itself a finding about the gene and the disease.
breast cancer (continued). "In contrast to NSCLC, GABARAP is also able to regulate epithelial-stromal transformation (EMT) in BC via the AKT/mTOR signaling pathway, thereby inhibiting the proliferation and invasion of breast cancer cells." (PMID 40900801, 2025). "Targeting PI3 K/AKT/mTOR signaling in breast cancer stem cells presents considerable potential to enhance clinical outcomes and long-term survival in breast cancer patients." (PMID 40676293, 2025). "In breast cancer, BCAT1 has been linked to mTOR signaling, enhancing mitochondrial function and cancer cell growth." (PMID 40083932, 2025). "Here, we demonstrate that human SPAR (hSPAR) acts as a tumor suppressor in breast cancer cells through P27KIP1-dependent/V-ATPase-independent mTOR inactivation mechanism." (PMID 39875724, 2025). "The conjugates of ω-3 PUFAs with ethanolamine were also shown to decrease the activation of the PI3K/Akt/mTOR signaling pathway in MCF-7 breast cancer cells, inducing cell death." (PMID 39863855, 2025). "Extracted from Brucea javanica, BO exhibited breast cancer suppression via gut microbiota modulation and mTOR pathway inhibition." (PMID 40299687, 2025). "PIK3CA mutations are common oncogenic mutations in breast cancer, and abnormal activation of the PI3K/AKT/mTOR pathway is a key mechanism underlying tumorigenesis and drug resistance." (PMID 41280894, 2025). "In breast cancer cells, treatment strategies targeting mTOR have been found to effectively inhibit the EMT process, thereby improving the effectiveness of chemotherapy." (PMID 40573188, 2025). "During the progression of endocrine resistance, following long‐term estrogen deprivation, PI3K primarily activates the mTOR substrate p70 ribosomal protein S6 kinase (p70S6K) in the human breast cancer cell lines MCF‐7 and MDA‐MB‐361." (PMID 40206206, 2025). "Overall, curcumin suppressed breast cancer cell growth and prompted G2/M phase cell cycle arrest and apoptosis, possibly by blocking Akt/mTOR phosphorylation and promoting mitochondrial apoptotic pathway." (PMID 39906716, 2025). "Many signalling pathways linked to breast cancer, such as JAK-STA, Hedgehog, Notch, PI3K/mTOR, and Wnt/β-Catenin, were successfully targeted by curcumin." (PMID 40427522, 2025). "This overactivation of the signaling pathway PI3K/AKT/mTOR increases cell proliferation and inhibits apoptosis, enhancing breast cancer development." (PMID 40227634, 2025). "The CDK1/cyclinD6/4 and PI3K/AKT/mTOR pathways have become a desirable target for the treatment of many cancers, with resistant breast cancer being one of them, as tumorigenesis is largely dependent on uncontrolled cell cycle progression." (PMID 41348684, 2025). "An increase in PI3K/AKT/mTOR signaling has been documented, contributing to proliferation via the NF-κβ pathway, metastasis, and drug resistance in breast cancer cells." (PMID 40035822, 2025). "By providing insights from retrospective clinical experience, this analysis contributes to the evolving understanding of endocrine resistance and the therapeutic role of mTOR inhibition in advanced breast cancer." (PMID 41002573, 2025). "This indicates that H2S acts on the PI3K/Akt/mTOR pathway in human breast cancer cells, and inhibiting the production of endogenous H2S can reduce cell proliferation and tumor growth through this signaling pathway." (PMID 40442106, 2025). "Mechanistically, TAS-115 downregulated c-MET and its downstream mTOR signaling, indicating a targeted disruption of survival and growth pathways in metastatic breast cancer cells." (PMID 41289612, 2025). "In contrast, mTOR inhibitors such as everolimus have approvals in breast cancer, renal cell carcinoma, and tuberous sclerosis." (PMID 41221048, 2025). "The interactions between Akt-mTOR pathway and estrogen receptor enable breast cancer cell to acquire estrogen tolerance during endocrine therapy." (PMID 41460862, 2025).
breast cancer (continued). "Studies have shown that knocking down GABARAPL1 in breast cancer cell lines can lead to inhibition of autophagy, which is regulated by the mTOR and AMPK signaling pathways." (PMID 40900801, 2025). "Although mTOR inhibitors for breast cancer treatment are currently at various stages of development, their therapeutic efficacy in TNBC remains significantly lower than in other types." (PMID 40949144, 2025). "When LIF binds to this complex, it activates a cascade of signaling pathways that include STAT, AKT, and mTOR, all of which are involved in the progression of breast cancer." (PMID 40075639, 2025). "Given the importance of the PI3K/AKT/mTOR pathway in breast cancer, numerous therapeutic strategies targeting this pathway have been developed." (PMID 40299687, 2025). "In this study, we provide an efficient drug development plan and a summary of the current understanding of the PI3K/AKT/mTOR pathway in relation to drug resistance in breast cancer." (PMID 39886047, 2025). "The PI3K-Akt pathway transmits signals from GPCRs, regulating downstream targets, such as mTOR, and, thereby, controlling breast cancer cell growth, apoptosis, and drug resistance." (PMID 40076902, 2025). "Multiple studies have consistently confirmed that inhibiting the expression of mTOR and its downstream target genes has a pronounced effect on halting the malignant progression of breast cancer." (PMID 40949144, 2025). "PI3K/Akt/mTOR signaling pathway, is one of the most common intracellular signaling pathways frequently abnormally activated in various cancer types, including breast cancer." (PMID 40042556, 2025). "This study provides compelling evidence that shikonin exerts antitumor activity in breast cancer cell lines by targeting the mTOR signaling pathway." (PMID 40949144, 2025). "The interplay between the Cyclin D1 and PI3K/AKT/mTOR signaling pathways in breast cancer is of paramount importance in tumor progression and drug resistance development." (PMID 41348684, 2025). "Major radiosensitizers relevant for breast cancer also include mTOR inhibitors, ATM inhibitors and PLK-4 inhibitors." (PMID 40667051, 2025). "Specifically, silibinin decreases phosphorylated mTOR protein levels, which in turn induces autophagy and inhibits the progression of liver cancer, breast cancer, and glioma." (PMID 40490812, 2025). "Further investigation into the biological functions of the differentially expressed IPA genes in TCGA breast cancer samples, particularly those regulated by mTOR signaling, revealed their involvement in critical oncogenic pathways." (PMID 41218079, 2025). "Human ncRNA-encoded micropeptide hSPAR counters breast cancer by enhancing P27KIP1 stability and P27KIP1-dependent mTOR inactivation." (PMID 39875724, 2025). "Clinical trials are now being conducted on a number of PI3 K/AKT/mTOR inhibitors for breast cancer, both alone and in combination." (PMID 40676293, 2025). "The complex intracellular pathway known as PI3K/Akt/mTOR promotes cell growth and tumor proliferation and is a major responsible factor in endocrine resistance in breast cancer." (PMID 40176859, 2025). "Targeted therapies, including CDK4/6 inhibitors and PI3K/AKT/mTOR inhibitors, such as PI3K inhibitors (e.g., alpelisib) have been approved for treating endocrine-resistant ER+ breast cancer, particularly in PIK3CA-mutated cases." (PMID 40427153, 2025). "It was suggested that the downregulation of miR-944 facilitates the expression of SPP1, which subsequently stimulates the PI3K/AKT/mTOR pathway in in vitro experiments with breast cancer cells." (PMID 40142329, 2025). "This study aims to comprehensively explore the interplay between estrogen receptor (ER) signaling and the PI3K/AKT/mTOR pathway in breast cancer, emphasizing its role in tumor progression, endocrine resistance, and therapeutic targeting." (PMID 40299687, 2025).
breast cancer (continued). "In patients with advanced (Stage III) HR+/HER2− breast cancer, mutations frequently occur in the phosphoinositide-3-kinase (PI3K)/protein kinase B (AKT)/mammalian target of rapamycin (mTOR) pathway, accounting for up to 40% of mutations in this population." (PMID 41155694, 2025). "In summary, our study has identified the TMEM45A/AKT/mTOR axis as a mediator of palbociclib resistance in breast cancer by promoting glycolysis and EMT in BRCA cells, highlighting its potential as a therapeutic target." (PMID 39910045, 2025). "The PI3K/AKT/mTOR signaling pathway is one of the most frequently activated pathways in breast cancer, regulating the proliferation and growth of tumor cells." (PMID 40949144, 2025). "Recent studies have demonstrated that NCAPH silencing significantly downregulates the AKT/mTOR signaling pathway, thereby inhibiting proliferation, migration, and invasion in breast cancer cells." (PMID 39991770, 2025). "The key molecular signaling involved in the regulation of aerobic glycolysis in breast cancer are the mTOR, PI3K/Akt, and AMPK pathways." (PMID 39858015, 2025). "In a study by Zhang and Han, elevated levels of BCAT1 were found to stimulate proliferation and mTOR activity in breast cancer." (PMID 40066850, 2025). "Certain breast cancer cells reduce sensitivity to PI3K/mTOR inhibitors by enhancing mTOR pathway activity through leucine metabolism." (PMID 40438606, 2025). "T-DM1 and the mTOR inhibitor everolimus demonstrated synergistic activity at inhibiting cell proliferation at multiple T-DM1 concentrations across four HER2-positive breast cancer cell lines." (PMID 40165206, 2025). "Thymol derivatives, such as 1,2,3‐triazoles and carvacrol, effectively target breast cancer (BC) through PI3K/AKT/mTOR and NOTCH pathways and inhibit PIK3CA expression." (PMID 40964147, 2025). "The role of A011 in mediating autophagy and apoptosis through the disruption of the PI3K/AKT/mTOR pathway highlights its potential as a therapeutic agent for breast cancer, emphasizing the importance of targeting autophagy mechanisms." (PMID 40740483, 2025). "LY01005, a GnRH agonist currently in clinical trials, aims to reduce estrogen levels, while Everolimus, an mTOR inhibitor, exerts anti-breast cancer effects through inhibition of the PI3K/Akt/mTOR pathway and activation of caspase-8-mediated apoptosis." (PMID 40649817, 2025). "The activated HER2/PI3K/AKT/mTOR signaling pathway positively correlated with SCD-1 and CD36 expression in PTEN-loss breast cancer cells." (PMID 39920872, 2025). "In our work, hSPAR-inhibited effect on mTOR activity occurs in breast cancer cells under complete culturing media and mice with regular diet." (PMID 39875724, 2025). "Our current work is consistent with a previous study in ER-positive PIK3CA-mutant breast cancer that identified aberrant mTOR signaling as a dominant mechanism of resistance to PIK3CA-targeted therapy." (PMID 39919177, 2025). "Further integrated with protein-protein interaction data, pathways of Jak-STAT, mTOR, MAPK and Wnt signaling are revealed in association with breast cancer recurrence." (PMID 39888956, 2025). "As the underlying mechanisms of these phenomena are still unclear, our study revealed that the AKT/mTOR pathway is involved in breast cancer and osteoblast interaction." (PMID 39980332, 2025). "For instance, in breast cancer, PSMD14 removes K63-linked ubiquitin chains from FOXM1 to activate the PI3K/AKT/mTOR pathway, thereby facilitating malignant progression." (PMID 41488674, 2025). "The development of breast cancer therapy involves targeting the mTOR pathway, not only as a standalone treatment but also in combination with other treatments." (PMID 40014262, 2025).
breast cancer (continued). "By potentially disrupting the PI3K/AKT/mTOR signaling pathway, these compounds offer a promising strategy for overcoming resistance in hormone-driven breast cancer." (PMID 40806603, 2025). "The selective blocker of SLC6A14, α-methyl-dl-tryptophan (α-MT), when used in vitro on ER-positive MCF7 breast cancer cells, can induce amino acid deprivation, inhibit mTOR, and activate autophagy." (PMID 39973065, 2025). "In breast cancer, miR-99a inhibits tumor growth by targeting the mammalian target of rapamycin (mTOR) pathway, reducing cell viability and promoting apoptosis." (PMID 40004152, 2025). "Gigantol has been shown to disrupt PI3K/Akt/mTOR signaling in breast cancer cells and to inhibit the PI3K/Akt/NF-κB pathway in hepatic cancer, leading to apoptotic cell death." (PMID 41154521, 2025). "Targeted radiosensitization strategies in breast cancer have focused on modulating PI3K/AKT/mTOR pathways to enhance therapeutic outcomes." (PMID 40652278, 2025). "Cancers with Tier II variants included bladder cancer, breast cancer, NSCLC, pancreatic cancer and sarcoma, and up to 76% of recurrent/metastatic cancer patients with Tier II variants received PI3K‐Akt–mTOR therapies through clinical trials." (PMID 40747594, 2025). "By interacting with the PI3K/AKT/mTOR pathway, salvianolic acid B, rutin, and chlorogenic acid have been shown to provide therapeutic benefits in managing diabetes, breast cancer, and esophageal cancer." (PMID 39972480, 2025). "Elevated expression of the mTOR signaling pathway is commonly recognized as a biological marker for breast cancer." (PMID 40943647, 2025). "This study suggests that DMDD inhibits the growth of breast cancer through the phosphatidylinositol‐3‐kinase (PI3K)/serine–threonine kinase (Akt)/mammalian target of rapamycin (mTOR) signaling pathway in vitro and in vivo." (PMID 39648951, 2025). "In breast cancer, IGSF10 plays a role in DNA repair, cell cycle regulation, and glycolysis, and is associated with the PI3K/Akt/mTOR and mTORC1 signaling pathways." (PMID 40598621, 2025). "5FU inhibits DNA synthesis, while EVE targets the mammalian target of rapamycin (mTOR) pathway, frequently dysregulated in breast cancer." (PMID 40165241, 2025). "Approximately 30–50% of breast cancer patients have a somatic alteration in the PI3 K/AKT/mTOR signaling pathway, driving tumor growth, proliferation, metabolism, and survival." (PMID 40471518, 2025). "For example, FOXA1, FOXA2, FOXC1, and FOXO3 can all interact with the PI3K/AKT/mTOR pathway and eventually regulate breast cancer cell proliferation." (PMID 40003882, 2025). "Reduced PD-L1 has been linked to changes in various oncogenic signalling pathways, including the AKT/mTOR pathway, which is frequently disrupted in breast cancer." (PMID 40008130, 2025). "PTEN is a negative regulator of intracellular phosphatidylinositol triphosphate levels, and is the main negative regulator of the PI3K/AKT/mTOR signal transduction pathway, which is typically downregulated in breast cancer 26,27." (PMID 39991583, 2025). "The PI3K/AKT/mTOR pathway is a central regulator of cell survival and is frequently hyperactivated in breast cancer, making it a prime therapeutic target." (PMID 40729015, 2025). "Though many studies have focused on PI3K/AKT/mTOR pathway in breast cancer, limited literature is available on the role of PI3K/AKT/mTOR pathway in breast CSCs." (PMID 40676293, 2025). "The phosphatidylinositol 3-kinase (PI3K)/AKT/mammalian target of rapamycin (mTOR) pathway is a crucial signal transduction system that is aberrantly activated in breast cancer, mediating cell proliferation, survival, metabolism, and metastasis." (PMID 41157306, 2025). "Despite the lack of further mTOR activation following chronic insulin stimulus, our findings indicate that both MCF-7 and MDA-MB-231 breast cancer cell lines exhibit a constitutively active mTOR pathway at baseline, a feature that is documented by other works." (PMID 40806650, 2025).
breast cancer (continued). "There are several clinical trials exploring various drug candidates that target the PI3K/AKT/mTOR pathway, implicating potent anticancer properties against resistance forms of breast cancer." (PMID 41348684, 2025). "SEH1L has emerged as a promising therapeutic target in various malignancies and other pathological conditions, and it plays a significant role in regulating the mechanistic target of rapamycin (mTOR) pathway in breast cancer." (PMID 40781725, 2025). "This study investigated the effects of PIK3CA mutations in breast cancer with respect to gene ontology and the PI3K/AKT/mTOR pathway." (PMID 40142329, 2025). "Palbociclib and other CDK4/6 inhibitors, for example, are now standard treatments for breast cancer, and everolimus and temsirolimus, mTOR inhibitors, are used clinically in oncology and tuberous sclerosis complex." (PMID 41221048, 2025). "Consistently, we collected clinical breast cancer specimens and detected the signals of hSPAR and p-mTOR, p-S6K and p-S6." (PMID 39875724, 2025). "In HER2-positive breast cancer cells, PIK3CA mutations and PTEN loss cause constitutive activation of PI3K/AKT/mTOR signals leading to oncogenesis as well as anti-HER2 resistance." (PMID 39920872, 2025). "When compared to everolimus (a first-generation MTOR inhibitor) in breast cancer cells, NVP-BEZ235 (a dual MTOR/PI3K inhibitor) had higher antiproliferative activity." (PMID 40564038, 2025). "CC1-779, an MTOR inhibitor, was used to treat breast cancer cell lines and inhibited MTOR activity and decreased c-myc expression." (PMID 40564038, 2025). "One of the main mechanisms responsible for endocrine resistance in HR+ breast cancer is the activation of the PI3K/AKT/mTOR pathway." (PMID 41002573, 2025). "The administration of nano-curcumin has been shown to reduce the expression of the Cyclin D1 and DILA1 genes, as well as downregulate the PI3K/AKT/mTOR signaling pathway, and furthermore, induce apoptosis in tamoxifen-resistant breast cancer cells." (PMID 41348684, 2025). "TRIB3 can regulate the PI3K / AKT / mTOR pathway to affect cellular energy metabolism, which has been confirmed in liver cancer, breast cancer, and oropharyngeal cancer." (PMID 39869954, 2025). "Everolimus has shown efficacy in breast cancer by inhibiting cell growth through downregulation of the PI3K/Akt/mTOR signaling pathway, highlighting its potential as a therapeutic option for primary breast AS." (PMID 40666093, 2025). "Further research is needed to confirm the safety and efficacy of mTOR inhibitors, such as rapamycin, for endometrial protection in patients with breast cancer undergoing tamoxifen therapy." (PMID 39819881, 2025). "Herein, the MSC-CM was impregnated with Wortmannin, a pan-PI3K/Akt/mTOR inhibitor, and their combined effect was investigated against breast cancer cells." (PMID 40038752, 2025). "The PI3K/AKT/mTOR signaling pathway is upregulated in breast cancer, contributing to both aerobic glycolysis and treatment resistance." (PMID 40303296, 2025). "Knockdown of lncRNA HOTAIR downregulates the drug resistance of breast cancer cells to doxorubicin via the PI3K/AKT/mTOR signaling pathway." (PMID 41329030, 2025). "This approach has shown particular promise in models of prostate and breast cancers, where combination treatments with mTOR and MEK inhibitors were more effective than single agents, including against hormone-refractory prostate cancer." (PMID 40729043, 2025). "For example, miR-760 targets the HM13 gene which performs oncogenic function by activating the PI3K/AKT/mTOR pathway and promoting cell proliferation in breast cancer." (PMID 40142329, 2025). "In vivo experiments confirmed that miR-944 plays the anticancer role, suppressing SPP1 and the PI3K/AKT/mTOR pathway in breast cancer." (PMID 40142329, 2025). "Another study reports TP53AIP1 as an inducer of autophagy through the AKT/mTOR signaling pathway in a breast cancer cell line." (PMID 40860288, 2025).